ALOX5 (arachidonate 5-lipoxygenase)
Diseases named in the same sentence as ALOX5 in open-access papers (continued):
Sharing a sentence is not in itself a finding about the gene and the disease.
rheumatoid arthritis (9 papers, 2014 to 2025). A chronic, systemic autoimmune disorder characterized by inflammation in the synovial membranes and articular surfaces. "Here, we identify ALOX5 as a previously unrecognized direct target of celastrol and further demonstrate that the ALOX5–macrophage axis drives bone destruction in rheumatoid arthritis through a novel transcriptional mechanism involving NF-κB/RELA." (PMID 41408107, 2025). "Arachidonic acid (AA)-regulated Ca2 + −selective (ARC) channels promote CD 4 + T cell pyroptosis and elevate the expression of ALOX5 in rheumatoid arthritis CD 4 + T cells." (PMID 40370665, 2025). "Moreover, ALOX5 regulates T cell pyroptosis in rheumatoid arthritis." (PMID 40370665, 2025).
Cerebral ischemia (8 papers, 2010 to 2022). Restriction of arterial blood supply to the brain associated with insufficient oxygenation to support the metabolic requirements of the tissue. "Inhibition of Alox5 translocation has been shown to protect against cerebral ischemia/reperfusion injury." (PMID 36231015, 2022). "An animal study demonstrated that caffeic acid (30 or 50 mg/ kg) ameliorates global cerebral ischemia-reperfusion injury in rats by inhibiting ALOX5." (PMID 34992531, 2021).
depression (8 papers, 2014 to 2025). "In summary, through bioinformatics and machine learning approaches, we have identified histone acetylation-related biomarkers ALOX5, JDP2, and KPNB1 associated with depression." (PMID 40370665, 2025). "Following the analysis of the metabolic pathways, seven genes including ALOX5, LTA4H, CYP4Y, PLA2G2C, AKR1C1, AKR1D1 and CYP17A1 were employed to elucidate further the potential mechanisms underlying CS treatment of depression." (PMID 40370520, 2025). "Because depression affects primarily the brain, we investigated some aspects of stress response in the hippocampus of 129sv and Alox5−/− mice." (PMID 31057373, 2019). "To investigate this hypothesis, we submitted Alox5−/− (5-LO deficient) and 129sv mice to chronic unpredictable stress (CUS), an experimental model that induces depression-like behaviors such as decreased sucrose preference." (PMID 31057373, 2019).
chronic myeloid leukemia (7 papers, 2011 to 2025). "Of note, among genes deregulated in the leukotriene pathway we identified ALOX5 (fold change = −4.36) and ALOX5AP (fold change = −2), where the loss of ALOX5 has been reported to impair leukemic stem cells and prevent the onset of chronic myeloid leukemia in mice." (PMID 31817495, 2019). "More recently, it was further demonstrated that ALOX5 is required for the induction of chronic myeloid leukemia (CML) by BCR-ABL, and a specific ALOX5 inhibitor is able to significantly delay CML onset when used either alone or in combination with the BCR-ABL kinase inhibitor imatinib." (PMID 24130502, 2013).
gastric ulcer (7 papers, 2015 to 2025). An ulcerated lesion in the mucosal surface of the stomach. "To further explore the underlying anti-inflammatory and anti-apoptotic molecular mechanisms of the CHRs, we performed IHC to detect the levels of ABCB1, ALOX5, NF-κB, Caspase9, and Bcl-2 in the stomach tissue of the mice with gastric ulcers." (PMID 40283949, 2025). "The results showed that the levels of ABCB1, ALOX5, NF-κB, and Caspase9 were significantly increased in the mice with gastric ulcers in the model group, but pretreatment with the CHRs reduced these expressions in a dose-dependent manner." (PMID 40283949, 2025).
Hypertension (7 papers, 2008 to 2024). The presence of chronic increased pressure in the systemic arterial system. "The up-regulated antisense lncRNA T041024 in C + T group was in proximity to the down-regulated ALOX5 gene implicated in hypertension." (PMID 31324852, 2019). "CYP3A4, APOA2, PPARG, ALOX, and CYP4F2, proteins related to lipid homeostasis affect the occurrence of hypertension, and PTGER2, ALOX5, LTF, ITGB, and GATA3 relate to the inflammatory and immune response in glomeruli." (PMID 30809144, 2019).
acute myeloid leukemia (6 papers, 2013 to 2024). Acute myeloid leukemia (AML) is a group of neoplasms arising from precursor cells committed to the myeloid cell-line differentiation. "On the other hand, ALOX5 overexpression in acute myeloid leukemia increased sensitivity to chemotherapy." (PMID 36839749, 2023). "While ALOX5 is also aberrantly expressed in several tumor types, it serves as a therapeutic target in acute myeloid leukemia, and it is upregulated in gefitinib‐resistant PC9/GR cells." (PMID 29901268, 2018). "Finally, we found that the MLL-AF4-related protein MLL-AF9, a driver of acute myeloid leukemia, similarly acts on the ALOX5 promoter." (PMID 39877387, 2024). "Instead, other reports show that ALOX5 may have opposite roles in a different context that it promoted BCR-ABL driven B-cell acute lymphoblastic leukemia while inhibited MLL-fusion driven acute myeloid leukemia." (PMID 36750552, 2023).
melanoma (6 papers, 2017 to 2025). A malignant, usually aggressive tumor composed of atypical, neoplastic melanocytes. "As a novel target in melanoma drug development, ALOX5 has been described to promote autophagy-dependent ferroptosis by activating the AMP-activated protein kinase (AMPK) pathway in vitro and in vivo." (PMID 38612771, 2024). "In the 9 gene signatures, by qRT-PCR, we found that significant differences in the expression of ABCC1, ACSL4 and ALOX5 between normal skin cell lines and melanoma cell lines." (PMID 35354376, 2022). "Indeed, the silencing of ALOX5 significantly reduced mitochondrial damage and increased the number of autophagosomes in erastin-treated melanoma cells (A375, A-875) demonstrating the occurrence of iron-dependent death and autophagy in the cells." (PMID 38612771, 2024). "In the prognostic model of melanoma patients with FRGs created by Xu and Chen, ALOX5 also formed their 5 gene signature as an indispensable member, and it was confirmed that its expression can be used as an independent prognostic factor to predict the OS of patients." (PMID 35354376, 2022). "We speculated that ferroptotic cells release lipid mediators such as LTB4 through ALOX5, to attract macrophages to the site of ferroptotic cells in melanoma." (PMID 34447410, 2021). "Our study showed that ALOX5 may improve survival rates in melanoma by inducing ferroptosis." (PMID 34447410, 2021). "In contrast, ALOX5, CISD1, ATP5MC3, NFS1, EMC2, ZEB1 are highly expressed in normal tissues, and they are related to the good prognosis of melanoma patients." (PMID 36313708, 2022). "We observed expressions of ferroptosis related proteins including ALOX5, PEBP1, ACSL4 and ZEB1 in melanoma, which showed a strong cytoplasmic staining." (PMID 36313708, 2022). "Although a previous study has shown an association between ALOX5 with poor outcome of tumor, there are no studies indicating association of ALOX5 with the prognosis of melanoma, we herein show for the first time that ALOX5 is associated with the prognosis of melanoma." (PMID 36313708, 2022). "In consent with previous studies that have highlighted the role of AIM2 (absent in melanoma 2) and ALOX-5 (arachidonate 5-lipoxygenase) genes in RA pathogenesis, our study also demonstrated the enhanced expression of these genes in RA patients as compared to HCs." (PMID 28210261, 2017).
atopic dermatitis (5 papers, 2024 to 2025). "Single-cell RNA sequencing (scRNA-seq) data from lesional atopic dermatitis (AD) skin biopsies, as reported in a previously published study, were re-analyzed to assess the expression of 5-lipoxygenase (5-LO/ALOX5) and leukotriene-C4-synthase (LTC4S)." (PMID 41296013, 2025). "However, acknowledging the ongoing importance of LC in atopic dermatitis, additional research is needed to elucidate how significant genetic factors (Trp73, Orm-1, Chi3l3, Ccl20, AnXa1, Alox5, Ccr1, and Fcεr1a, etc.)identified in our study may interact with LC function and the disease process." (PMID 38834629, 2024).
cervical carcinoma (5 papers, 2021 to 2026). A carcinoma arising from either the exocervical squamous epithelium or the endocervical glandular epithelium. "Furthermore, TNFRSF12A was found to act as a C2 ALOX5+ MCs and tumor cell key receptor in the communication pathway that plays a role in cervical cancer progression." (PMID 40391219, 2025). "However, the other five compounds upregulated ALOX5 expression in cervical carcinoma cells." (PMID 41339896, 2025).
glioblastoma (5 papers, 2016 to 2021). The most malignant astrocytic tumor (WHO grade IV). "Lipid metabolism enzymes, ACSVL3 (acyl-CoA synthetase very-long-chain 3) and ALOX5 (arachidonic acid 5-lipoxygenase) promoted glioblastoma CSCs self-renewal and tumorigenicity." (PMID 34804950, 2021).
neuroblastoma (5 papers, 2010 to 2022). Neuroblastoma (NB) is the most common solid, extracranial childhood tumor. "Low PPARδ and ALOX5 expression was associated with MYCN amplification in a cohort of 251 primary neuroblastoma tumours." (PMID 23874790, 2013). "The expression of PPARδ1 and ALOX5 were examined across the following groups: stages 1 & 2, stage 3, stage 4, stage 4S and MYCN amplified neuroblastoma." (PMID 23874790, 2013). "The mechanism linking low PPARδ1 and ALOX5 to MYCN amplification status in neuroblastoma needs to be investigated, and the study raises questions over the potential role of PPARδ1 in promoting cell survival signalling in neuroblastoma." (PMID 23874790, 2013).
aortic aneurysm (4 papers, 2018 to 2022). A ruptured aneurysm located in the wall of the proximal portion of the descending aorta proceeding from the arch of the aorta. "Another study showed downregulation of miRNA-125b-5p and miR-193a-3p in aortic aneurysm tissues, leading to increased leukotriene production, increased inflammation and aortic wall damage through upregulation of the ALOX5 gene." (PMID 36011386, 2022).
brain injury (4 papers, 2009 to 2025). Acute and chronic (see also brain INJURIES, CHRONIC) injuries to the brain, including the cerebral hemispheres, CEREBELLUM, and brain STEM. "For example, we identified target genes that encode enzymes involved in prostaglandin biosynthesis and in modulating AS activation in response to brain injuries, including Alox5 and Ptgs2." (PMID 19888342, 2009).
colon adenoma (4 papers, 2011 to 2021). An adenoma that arises from the colon. "ALOX5 is overexpressed during the process of colonic adenoma formation promoted by cigarette smoke." (PMID 34121352, 2021).
endothelial dysfunction (4 papers, 2014 to 2025). In vascular diseases, endothelial dysfunction is a systemic pathological state of the endothelium (the inner lining of blood vessels) and can be broadly defined as an imbalance between vasodilating and vasoconstricting substances produced by (or acting on) the endothelium. "In addition to HIF and Egr-1, the ALOX5 promoter region also contains binding sites for TGF-β and NF-κB, which are also implicated in the endothelial dysfunction and vascular remodeling in PH pathogenesis." (PMID 24906007, 2014).
hemorrhagic stroke (4 papers, 2022). A stroke caused by a bleed on the brain. "Another study has shown that N-acetylcysteine (NAC) targets ALOX5 derived toxic lipids and can synergize with prostaglandin E 2 to inhibit ferroptosis and improve outcomes following hemorrhagic stroke in mice." (PMID 36407421, 2022). "Previous study found that inhibition of ALOX5 expression could decrease ferroptosis in nerve cells derived from hemorrhagic stroke mice." (PMID 35354376, 2022).
inflammatory bowel disease (4 papers, 2020 to 2025). A spectrum of small and large bowel inflammatory diseases of unknown etiology. "HCK was previously found to be genetically associated with inflammatory bowel disease and predicted as a causal factor that regulates NOD2, IL10 and ALOX5." (PMID 32565911, 2020).
ischemic stroke (4 papers, 2006 to 2021). A stroke disorder caused by obstruction of blood flow to the brain, due to thrombotic (local blood clot formation) or embolic (due to a blood clot or other material traveling from another site) event. "Moreover, recent studies have identified several predisposing genes that are also corelated with an ischemic stroke risk, such as LTC4S, ALOX5, APOA1, APOB." (PMID 33808851, 2021).
multiple sclerosis (4 papers, 2019 to 2025). A progressive autoimmune disorder affecting the central nervous system resulting in demyelination. "It suppresses the systemic production of arachidonate 5-lipoxygenase (ALOX5), cyclooxygenase (COX) 1, and COX2, which are essential for the synthesis of pro-inflammatory eicosanoids and linked to inflammation and demyelination in multiple sclerosis." (PMID 40149775, 2025). "Moreover, microarray analyses identified ALOX5 as a component of inflammatory brain lesions in human multiple sclerosis and in the EAE mouse model." (PMID 34677413, 2021).
periodontitis (4 papers, 2020 to 2025). An acute or chronic inflammatory process that affects the tissues that surround and support the teeth. "The qRT-PCR results revealed upregulation of IL-1β, IL-6 and ALOX5 in the periodontitis group and further upregulation in the periodontitis with T2DM group, while the expression of NFE2L2 was the opposite." (PMID 36248844, 2022). "Compared with the control group, the mRNA expression levels of IL-1β, IL-6 and ALOX5 were increased in the periodontitis group and further increased in the periodontitis with T2DM group." (PMID 36248844, 2022). "Compared with T2DM patients with healthy periodontal conditions, T2DM patients with periodontitis exhibit significantly higher expression of ferroptosis-related genes, such as IL-1β, IL-6, NFE2L2, and ALOX5, in pancreatic tissue." (PMID 40541947, 2025). "In our results, not only was ALOX5 overexpressed, but we also encountered a situation in which LPS was present given that periodontitis predominantly presents microbiota of Gram-negative bacteria." (PMID 32764374, 2020). "The molecular docking results showed that BBR can effectively bind to periodontitis targets ALOX5, AKT1, NOS2, and TNF, indicating that these four targets have high biological activity and can serve as potential biomarkers and key therapeutic targets for BBR treatment of periodontitis." (PMID 38704553, 2024).
cardiac ischemia (3 papers, 2013 to 2022). "Targeting RNAi at ALOX5 resulted in a 19% decrease in ALOX5 expression in myocardial tissue and a 3.8-fold reduction in infarct size in experiments in a rat model of myocardial ischemia-reperfusion." (PMID 36011386, 2022).
cholangiocarcinoma (3 papers, 2023 to 2025). A carcinoma that arises from the intrahepatic biliary tree (intrahepatic cholangiocarcinoma) or from the junction, or adjacent to the junction, of the right and left hepatic ducts (hilar cholangiocarcinoma). "As a previous study indicated that STAT3 could bind to the promoter region of ALOX5 in cholangiocarcinoma, we started to determine whether PIK3CAmut stimulated 5‐LOX expression by regulating the phosphorylation of Akt and STAT3 in vitro." (PMID 37965796, 2023).
colorectal adenocarcinoma (3 papers, 2012 to 2022). The most common type of colorectal carcinoma. "Data on 594 colorectal adenocarcinoma revealed that FPR1 mRNA levels significantly and directly correlated with mRNA expression levels of the proresolving factors ALOX5 and ALOX15B." (PMID 35808840, 2022).
colorectal polyp (3 papers, 2019 to 2023). "ALOX5 rs4986832 polymorphism did not have any association with the risk of colorectal polyps." (PMID 35928873, 2022). "Furthermore, we detected the expressions of ALOX5, ALOX12, ALOX15 and ALOX15B in colorectal polyp." (PMID 31528237, 2019).
fatty liver disease (3 papers, 2020 to 2024). A reversible condition wherein large vacuoles of triglyceride fat accumulate in liver cells via the process of steatosis. "Our results also showed that miR‐30a‐5p regulated gut microbiota through ALOX5, ALOX12 and COX2 – key enzymes of the arachidonic acid pathway – affecting hepatic steatosis and dyslipidaemia in mice." (PMID 39360667, 2024). "Similarly, our findings revealed that the deletion of miR‐30a‐5p after HFD increased the expression of ALOX5 and ALOX12, which further led to hepatic steatosis through lipid peroxidation of the liver." (PMID 39360667, 2024).
heart failure (3 papers, 2024 to 2025). Inability of the heart to pump blood at an adequate rate to meet tissue metabolic requirements. "Our previous studies showed that inhibiting Alox5 could improve stress overload‐induced heart failure and septic cardiomyopathy." (PMID 40485049, 2025). "The screened hub genes, including OGN, FOS and ALOX5, were validated using single-cell sequencing data, cell lines and human samples, which can be therapeutic targets for the treatment to cell senescence under hypoxia and prediction to heart failure progression to HFpEF." (PMID 40060963, 2025). "Zileuton, which was an Alox5‐specific inhibitor, was used to treat DIC, including heart failure and septic cardiomyopathy." (PMID 40485049, 2025). "Ablation of Alox5 in bone marrow-derived cells did not affect pathological cardiac remodeling and heart failure." (PMID 40060963, 2025). "FOS and ALOX5 were mainly expressed in macrophages and OGN was mainly expressed in fibroblasts, which were all significantly expressed in disease progression and required more attention to explore the effects on heart failure." (PMID 40060963, 2025). "Alox5 belongs to a class of nonheme iron-containing dioxygenases involved in the catalysis of leukotriene biosynthesis, which was essential for biosynthesis of specialized pro-resolving mediators and cardiac repair in heart failure." (PMID 40060963, 2025).
intrahepatic cholangiocarcinoma (3 papers, 2023 to 2025). A carcinoma that arises from the intrahepatic bile duct epithelium in any site of the intrahepatic biliary tree. "Moreover, lipid metabolites such as leukotriene B4 (LTB4), produced via Arachidonate 5-lipoxygenase (ALOX5) from arachidonic acid, recruit M2 macrophages by activating the PI3K pathway, promoting tumor progression in intrahepatic cholangiocarcinoma." (PMID 41488672, 2025).
liver fibrosis (3 papers, 2004 to 2021). "As an inhibitor of ALOX5, caffeic acid may thus be able to attenuate liver fibrosis via this ALOX5 pathway." (PMID 30923657, 2019). "Among the target genes corresponding to these compounds, we found that HTR2B, ABCB1, and ALOX5 were significantly up-regulated in HBV and HCV related liver fibrosis datasets (Data not show)." (PMID 30923657, 2019).
lung adenocarcinoma (3 papers, 2021 to 2026). A carcinoma that arises from the lung and is characterized by the presence of malignant glandular epithelial cells. "In this study, ALOX5 expression was markedly reduced in lung adenocarcinoma tumours and this finding was reproducibly observed in the TCGA RNA Seq datasets." (PMID 34203378, 2021). "We propose that a secondary consequence of reduced ALOX5 expression in lung adenocarcinoma is that the production of SPMs such as RvD1 and AT-RvD1 will also be reduced in the tumour microenvironment." (PMID 34203378, 2021). "The biosynthesis of AT-RvD1 is dependent on the ALOX5 gene, and we reveal that ALOX5 mRNA expression was markedly reduced in lung adenocarcinoma tumours." (PMID 34203378, 2021). "Tumour expression of SAA and ALOX5 were analysed by RTqPCR and an oncogenic KrasG12D lung adenocarcinoma mouse model was used to investigate the in vivo efficacy of AT-RvD1 treatment." (PMID 34203378, 2021). "ALOX5 expression was markedly reduced in lung adenocarcinoma tumours." (PMID 34203378, 2021). "We have identified that a subset of lung adenocarcinoma patients express higher levels of SAA relative to ALOX5 and that the SAA/ALOX5 ratio positively correlates with neutrophil infiltration." (PMID 34203378, 2021). "Since ALOX5 is reduced in lung adenocarcinoma and required for AT-RvD1 production, we next evaluated the therapeutic potential of this SPM in the well-established KrasG12D lung adenocarcinoma model." (PMID 34203378, 2021).